ABCB8 (ATP binding cassette subfamily B member 8)
Description:
ATP-binding subunit of the mitochondrial ATP-gated potassium channel (mitoK(ATP)). Together with pore-forming subunit CCDC51/MITOK of the mitoK(ATP) channel, mediates ATP-dependent potassium currents across the mitochondrial inner membrane. An increase in ATP intracellular levels closes the channel, inhibiting K(+) transport, whereas a decrease in ATP levels enhances K(+) uptake in the mitochondrial matrix. Plays a role in mitochondrial iron transport. Required for maintenance of normal cardiac function, possibly by influencing mitochondrial iron export and regulating the maturation of cytosolic iron sulfur cluster-containing enzymes (By similarity).
Synonyms: M-ABC1; MITOSUR; MABC1; EST328128
Tractability: Small molecule: a structure with a bound ligand is known; it belongs to a druggable protein family. Antibody: UniProt predicts a signal peptide or a membrane-spanning region. PROTAC: ubiquitination databases record sites on it; its protein half-life has been measured.
Gene: Protein-coding gene on chromosome 7 (151,028,422 to 151,047,782, forward strand). Ensembl gene ENSG00000197150.
Subcellular location: Mitochondrion inner membrane
Subcellular location (Human Protein Atlas): Mitochondria; Nucleoli; Nucleoplasm
Pathways (Reactome):
Transport of small molecules: Mitochondrial ABC transporters
Gene Ontology:
Molecular function: ATP binding; protein binding; ABC-type transporter activity; ATP hydrolysis activity
Biological process: cell volume homeostasis; mitochondrial potassium ion transmembrane transport; potassium ion transmembrane transport; transmembrane transport
Cellular component: mitochondrial ATP-gated potassium channel complex; mitochondrial inner membrane; mitochondrial membrane; mitochondrion; ATP-binding cassette (ABC) transporter complex; membrane
Genetic constraint (gnomAD): Loss-of-function variants: 52 observed, 73.29 expected, observed/expected ratio (o/e) 0.71, 90% interval 0.57 to 0.89. The upper end of that interval is the gene's LOEUF score, 0.89, which puts it in group 3 of 6, group 1 being the genes least tolerant of losing a copy. Missense variants: 909 observed, 990.77 expected, observed/expected ratio (o/e) 0.92, 90% interval 0.87 to 0.97. Synonymous variants: 428 observed, 433.88 expected, observed/expected ratio (o/e) 0.99, 90% interval 0.91 to 1.07.
Homologues: Orthologues: chimpanzee ABCB8 (99% identical), macaque ABCB8 (96% identical), rabbit ABCB8 (90% identical), guinea pig ABCB8 (84% identical), mouse Abcb8 (84% identical), dog ABCB8 (83% identical), rat Abcb8 (83% identical), pig ABCB8 (75% identical), zebrafish abcb8 (59% identical), tropical clawed frog abcb8 (58% identical), Caenorhabditis elegans pgp-1 (29% identical), Caenorhabditis elegans haf-7 (29% identical), and 7 more. Paralogues in human: ABCB10 (34% identical), ABCB9 (31% identical), TAP2 (31% identical), ABCB1 (30% identical), ABCB4 (29% identical), ABCB11 (28% identical), ABCB5 (28% identical), TAP1 (27% identical), ABCB6 (25% identical), ABCB7 (23% identical).
Diseases named in the same sentence as ABCB8 in open-access papers:
ABCB8 is named in the same sentence as 16 diseases in open-access papers, as found by Europe PMC text mining. Sharing a sentence is not in itself a finding about the gene and the disease. The quoted sentences say what the papers report.
cardiomyopathy (8 papers, 2016 to 2025). A disease of the heart muscle or myocardium proper. "Deletion of Abcb8 in mouse heart leads to cytosolic Fe/S cluster deficiency and spontaneous cardiomyopathy." (PMID 33835027, 2021). "It is also worth pointing out that elevated iron level has been causally linked to the cardiomyopathy phenotype in mice with cardiac-specific ABCB8 deletion." (PMID 33835027, 2021). "Similarly phenotypic data links ABCB8 to iron homeostasis as a mutation of Abcb8 results in cardiomyopathy with increased mitochondrial iron accumulation with decreased activity of cytosolic Fe-S clusters proteins." (PMID 35669513, 2022). "Conversely, Doxorubicin treatment of mice with ABCB8 deletion in the heart exacerbated cardiomyopathy." (PMID 32911833, 2020). "Supporting a crucial role of ABCB8 in regulating iron homeostasis, ABCB8 mutants overexpressing ABCB8 are protected from cardiomyopathy induced by Doxorubicin, an anticancer drug known to induce iron-dependent oxidative stress in cardiomyocytes and cardiotoxicity." (PMID 32911833, 2020). "Deletion of ABCB8, another mitochondrial transporter has been shown to lead to accumulation of ROS, impairment of iron export, and maturation of heme and iron-sulfur cluster proteins and contribute to cardiomyopathy in mice." (PMID 31511561, 2019). "We next took a loss‐of‐function approach and studied whether a decrease in mitochondrial iron in cardiac‐specific ABCB8 knockout mice, a model of spontaneous cardiomyopathy with mitochondrial iron overload, protects against cardiac tissue damage." (PMID 26896449, 2016). "Additionally, BPD‐treated ABCB8 KO mice demonstrated attenuated expression of Nppa, Nppb, and Myh7, which are upregulated in cardiomyopathy." (PMID 26896449, 2016). "Mouse mutants lacking ABCB8 expression in the heart have compromised systolic and diastolic function and show cardiomyopathy, fibrosis but no obvious signs of heart failure after 8 weeks from gene deletion." (PMID 32911833, 2020). "Accordingly, mouse mutants lacking ABCB8 expression in cardiomyocytes develop cardiomyopathy due to increased mitochondrial iron, which results in iron-dependent ROS production and mitochondrial dysfunction." (PMID 30623799, 2019).
melanoma (4 papers, 2019 to 2022). A malignant, usually aggressive tumor composed of atypical, neoplastic melanocytes. "ABCB8 mediates doxorubicin resistance by protecting the mitochondrial genome in melanoma." (PMID 35874705, 2022). "In human SK-MEL-30 melanoma cells treated with 250 ng/mL hGH in vitro increased expression of ABCB5, ABCB8, ABCG1 and ABCG2 RNA." (PMID 33291663, 2020).
atherosclerosis (2 papers, 2015 to 2025). A disease characterized by the build-up of fatty material and calcium deposition in the arterial wall resulting in partial or complete occlusion of the arterial lumen. "We demonstrate that loss of ABCB8 promotes a pro-inflammatory environment in the aortic wall, exacerbates atherosclerosis, and contributes to vascular dysfunction and hypertension." (PMID 41252867, 2025). "In agreement, endothelial ABCB8 deficiency exacerbates atherosclerosis and hypertension in Apoe−/− knockout mice, uncovering a critical atheroprotective role for ABCB8 and supporting its therapeutic potential in vascular disease." (PMID 41252867, 2025). "In the Chr 5 locus, there are 4 hepatic genes with eQTL that are in strong LD with the atherosclerosis associated SNP at the locus: Nub1 (p = 1.65×10−16), Nos3, (p = 3.08×10−6), Cdk5 (p = 2.48×10−5), and Abcb8 (p = 7.46×10−4)." (PMID 26694027, 2015). "In this study, we investigated the role of endothelial ABCB8 in vascular inflammation and atherosclerosis." (PMID 41252867, 2025). "Our data show increased atherosclerosis plaque burden in Abcb8ECKO; Apoe−/−, demonstrating that ABCB8 is atheroprotective and supporting a role of iron in atherosclerosis." (PMID 41252867, 2025). "Immunostaining showed a significant increase in Collagen I and MMP2 in the aorta of Abcb8ECKO mutants, corroborating the scRNAseq data and indicating that Abcb8 loss induces collagen synthesis and MMP-2 levels, both known to play a role in atherosclerosis plaque development." (PMID 41252867, 2025). "Our data suggest that strategies promoting ABCB8 function or inhibiting iron-dependent TGF-β signalling in the endothelium could be beneficial to reverse vascular inflammation in patients with cardiovascular disease, in which atherosclerosis is an underlying condition." (PMID 41252867, 2025). "Overall, our data suggest that therapeutic strategies aimed at enhancing ABCB8 function or modulating iron-dependent TGF-β signalling could hold promise for mitigating vascular inflammation and atherosclerosis." (PMID 41252867, 2025).
brain tumors (1 paper, 2022). "ABCB8 is an interesting candidate gene associated with brain tumors that encodes an ATP-binding subunit of the mitochondrial potassium channel." (PMID 35545612, 2022). "Further experiments are crucial to confirm whether deleterious ABCB8 mutations increase the risk to adult brain tumors." (PMID 35545612, 2022).
breast carcinoma (1 paper, 2018). "Studies have reported that ABCB5, ABCB8, ABCB10, ABCC2–5, and ABCC10 are overexpressed in breast cancer cells or are associated with breast cancer progression." (PMID 30202239, 2018). "ABCB1, ABCB5, ABCB8, ABCC1, ABCC2, ABCC3, and ABCG2 were considered to confer resistance to doxorubicin on the breast cancer cells." (PMID 30202239, 2018).
clear-cell renal cell carcinoma (1 paper, 2022). "ABCB8 is overexpressed in phenotypically aggressive clear-cell renal cell carcinoma and plays a role in promoting the growth of renal clear cell carcinoma." (PMID 36185204, 2022).
hereditary hemochromatosis (1 paper, 2026). An inherited metabolic disorder characterized by iron accumulation in the tissues. "While conflicting reports exist, in a mouse model of hereditary hemochromatosis, changes in cardiac ABCB8 expression were reported to regulate DOX retention and cardiotoxicity, with decreased ABCB8 corresponding to DOX retention and ABCB8 overexpression corresponding with DOX efflux." (PMID 41545030, 2026).
iron deficiency (1 paper, 2022). "In several cancers, the efflux and resistance against doxorubicin (DOX), an effective anticancer drug, are associated with cellular iron deficiency and overexpression of the mitochondrial exporter ABCB8." (PMID 35359834, 2022). "Western blot and qPCR analyses revealed that ABCB8 levels were decreased in iron overload and increased in iron deficiency." (PMID 35359834, 2022). "Consistent with ABCB8 expression, DOX retention was increased in iron-loaded cardiomyocytes, whereas iron deficiency dramatically decreased cardiac DOX retention." (PMID 35359834, 2022). "In addition, ABCB8 downregulation caused by DOX treatment was exacerbated by iron overload and rescued by iron deficiency." (PMID 35359834, 2022).
ischemia (1 paper, 2025). A hypoperfusion of the BLOOD through an organ or tissue caused by a PATHOLOGIC CONSTRICTION or obstruction of its BLOOD VESSELS, or an absence of BLOOD CIRCULATION. "Thus, while cellular stress such as ischemia may induce mitochondrial K+ influx via a CCDC51/ABCB8 channel, we propose this is counterbalanced by a ROMK2/SUR2A-55 channel promoting K+ efflux." (PMID 40332433, 2025).
tumor (3 papers, 2022 to 2024). "The expression levels of ABCB8 and ACO1 in CM were negatively correlated with the prognostic risk of the tumor." (PMID 38874871, 2024). "Therefore, it is now possible to test this hypothesis, for example, in a sufficiently large sample size to determine if ABCB8 is overexpressed in human doxorubicin‐resistant tumor samples versus treatment‐naïve tumor samples." (PMID 35906899, 2023). "Additionally, further application of spatial transcriptomics technology to in vivo doxorubicin‐tumor response models would allow visualization of the clonal expansion and emergence of ABCB8‐mediated resistance over the time‐course of doxorubicin tumor treatment." (PMID 35906899, 2023). "The downregulation of ABCB8 and ACO1 can enhance CM cell proliferation, migration and invasion capabilities, thus promoting the development of tumor." (PMID 38874871, 2024).
cancer (1 paper, 2022). A tumor composed of atypical neoplastic, often pleomorphic cells that invade other tissues. "In DOX-resistant cancers, which are associated with ABCB8 overexpression, cellular iron levels are decreased." (PMID 35359834, 2022). "While ABCB8 is associated with DOX efflux and resistance in several cancers, its role in cardiac DOX efflux remains to be established." (PMID 35359834, 2022). "Interestingly, DOX cardiotoxicity is associated with cardiac iron accumulation and dose-dependent depletion of ABCB8, whereas DOX resistance in cancer is commonly associated with ABCB8 overexpression and unchanged or deficient cellular iron." (PMID 35359834, 2022). "The mitochondrial exporter, ABCB8, is frequently up-regulated in DOX-resistant cancers, and correcting ABCB8 expression restores sensitivity to DOX." (PMID 35359834, 2022).
ABCB8 also shares sentences with these, for which no sentence is quoted: endothelial dysfunction (2 papers); cardiovascular disease (1); glioma (1); Hypertension (1); Nonalcoholic Steatohepatitis (1).